UNG (uracil DNA glycosylase)
Description:
Uracil-DNA glycosylase that hydrolyzes the N-glycosidic bond between uracil and deoxyribose in single- and double-stranded DNA (ssDNA and dsDNA) to release a free uracil residue and form an abasic (apurinic/apyrimidinic; AP) site. Excises uracil residues arising as a result of misincorporation of dUMP residues by DNA polymerase during replication or due to spontaneous or enzymatic deamination of cytosine. Mediates error-free base excision repair (BER) of uracil at replication forks. According to the model, it is recruited by PCNA to S-phase replication forks to remove misincorporated uracil at U:A base mispairs in nascent DNA strands. Via trimeric RPA it is recruited to ssDNA stretches ahead of the polymerase to allow detection and excision of deaminated cytosines prior to replication. The resultant AP sites temporarily stall replication, allowing time to repair the lesion. Mediates mutagenic uracil processing involved in antibody affinity maturation. Processes AICDA-induced U:G base mispairs at variable immunoglobulin (Ig) regions leading to the generation of transversion mutations. Operates at switch sites of Ig constant regions where it mediates Ig isotype class switch recombination. Excises AICDA-induced uracil residues forming AP sites that are subsequently nicked by APEX1 endonuclease. The accumulation of staggered nicks in opposite strands results in double strand DNA breaks that are finally resolved via non-homologous end joining repair pathway (By similarity).
Synonyms: UDG; DGU; UNG1; UNG15; UNG2; HIGM4; HIGM5
Tractability: Small molecule: a structure with a bound ligand is known; it has a binding pocket of medium quality. PROTAC: ubiquitination databases record sites on it; its protein half-life has been measured; a small molecule that binds it is known.
Target class: Enzyme; Hydrolase
Gene: Protein-coding gene on chromosome 12 (109,097,572 to 109,126,725, forward strand). Ensembl gene ENSG00000076248.
Subcellular location: Mitochondrion (Isoform 1); Nucleus (Isoform 2)
Subcellular location (Human Protein Atlas): Nucleoplasm; Mitochondria
Pathways (Reactome):
DNA Repair: Cleavage of the damaged pyrimidine; Displacement of DNA glycosylase by APEX1; Recognition and association of DNA glycosylase with site containing an affected pyrimidine
Developmental Biology: Chromatin modifications during the maternal to zygotic transition (MZT)
Gene Ontology:
Molecular function: damaged DNA binding; protein binding; ribosomal small subunit binding; uracil DNA N-glycosylase activity; hydrolase activity, hydrolyzing N-glycosyl compounds
Biological process: base-excision repair, AP site formation via deaminated base removal; depyrimidination; single strand break repair; base-excision repair; DNA repair; negative regulation of apoptotic process
Cellular component: mitochondrion; nucleoplasm; nucleus
Genetic constraint (gnomAD): Loss-of-function variants: 34 observed, 37.1 expected, observed/expected ratio (o/e) 0.92, 90% interval 0.7 to 1.22. The upper end of that interval is the gene's LOEUF score, 1.22, which puts it in group 5 of 6, group 1 being the genes least tolerant of losing a copy. Missense variants: 391 observed, 408.41 expected, observed/expected ratio (o/e) 0.96, 90% interval 0.88 to 1.04. Synonymous variants: 172 observed, 161.7 expected, observed/expected ratio (o/e) 1.06, 90% interval 0.94 to 1.21.
Gene-disease validity (ClinGen):
ClinGen rates the evidence that UNG causes each of these diseases.
hyper-IgM syndrome type 5 (autosomal recessive): Moderate. Any hyper-IgM syndrome in which the cause of the disease is a mutation in the UNG gene.
Homologues: Orthologues: chimpanzee UNG (100% identical), macaque UNG (97% identical), dog UNG (92% identical), rabbit UNG (90% identical), pig UNG (89% identical), guinea pig UNG (87% identical), rat Ung (87% identical), mouse Ung (85% identical), tropical clawed frog ung (71% identical), zebrafish unga (66% identical), zebrafish ungb (56% identical), Caenorhabditis elegans ung-1 (43% identical).
Diseases named in the same sentence as UNG in open-access papers:
UNG is named in the same sentence as 72 diseases in open-access papers, as found by Europe PMC text mining. Sharing a sentence is not in itself a finding about the gene and the disease. The quoted sentences say what the papers report.
B cell lymphoma (9 papers, 2012 to 2023). "Thus, the UNG enzyme deficiency may on the one hand be responsible for immunological dysregulation and on the other hand may lead to development of B-cell lymphomas in the case of AID mistargeting." (PMID 33921666, 2021). "However, UNG knockouts displayed a 22-fold increase in malignancies of B-cell lymphomas late in life, preceded by lymphatic hyperplasia." (PMID 33921666, 2021). "UNG expression was negatively correlated with APOBEC3B expression in mature B cell lymphoma cell lines (MATBCL; ρ = − 0.372, padj = 0.034, n = 60, Ntests = 230) and with APOBEC3A expression in chronic lymphocytic leukemia cells (CLLE; ρ = − 0.324, padj = 0.037, n = 78, Ntests = 230)." (PMID 29642934, 2018). "Nevertheless, knock out mice for the UNG gene are prone to B cell lymphomas." (PMID 22992442, 2012). "Thus, our data provide direct evidence that UNG is a brake to AID-induced intratumoral heterogeneity and evolution of B cell lymphoma." (PMID 33362210, 2020). "Furthermore, UNG and SMUG1 expression has recently been found to correlate negatively with genomic uracil levels in B cell lymphomas." (PMID 28362259, 2017). "Interestingly, they develop lymphoid hyperplasia and B-cell lymphomas, indicating that the lack of UNG disrupts the adaptive immunity." (PMID 29967751, 2018). "UNG deficiency blocks the proliferation of tumor B cells expressing AID (Activation-induced deaminase), which deaminates nonimmunoglobulin genes, may cause B cell lymphoma if failure to faithfully repair these off-target lesions." (PMID 31194807, 2019).
colorectal cancer (7 papers, 2006 to 2025). A primary or metastatic malignant neoplasm that affects the colon or rectum. "Here we explore the effects of inhibiting UNG activity, or depleting the UNG protein, in 2 mouse syngeneic models for colorectal cancer." (PMID 40663394, 2025).
lung carcinoma (7 papers, 2016 to 2024). "So far, UNG rs246079 A/G SNP is associated with the susceptibility of rheumatoid arthritis in Taiwan’s Han Chinese population and increased lung cancer risk." (PMID 31415677, 2019). "The authors also described patients with either homozygous variant A/A or heterozygous A/G variant of rs3131379 (c.813-45G>A) as susceptible towards lung cancer, this tendency was more pronounced among individuals who carried UNG (uracil DNA glycosylase) rs246079 SNP (c.802-574A>G)." (PMID 32756484, 2020). "Targeted therapy-induced transcriptional changes of A3B and UNG were assessed in established human lung cancer cell line data from publicly available datasets (Gene Expression Omnibus (GEO) database, GEO2R)." (PMID 38049664, 2024). "UNG is a critical mediator of pemetrexed sensitivity in lung cancer." (PMID 33102573, 2020). "Mutations and single nucleotide polymorphisms (SNPs) in BER genes are associated with numerous cancers, such as UNG2 (uracil DNA glycosylase) mutations in glioblastoma, MED1 (mediator complex subunit 1) mutations in colorectal cancer, and OGG1 (8-oxoguanine DNA glycosylase) mutations in lung cancer." (PMID 26967246, 2016).
breast carcinoma (6 papers, 2011 to 2022). "Likewise, we confirmed the up-regulation of seven genes (BID, MRRL17, SH3PB5, MRRL49, TK1, TIMM10, and UNG) in rho0 cells and breast cancer cell lines." (PMID 21935467, 2011).
hyper-IgM syndrome (6 papers, 2016 to 2022). A primary immune deficiency disorder characterized by defective CD40 signaling; via B cells affecting class switch recombination (CSR) and somatic hypermutation. "For example, deficiency of UNG or Msh6 results in primary human immunodeficiency presenting as a class-switching defect, also called Hyper-IgM syndrome." (PMID 29389970, 2018). "Defects in uracil DNA glycosylase (UNG) result in an extreme immunodeficiency known as Hyper-IgM syndrome due to the central role of this enzyme in antibody diversification." (PMID 35935942, 2022). "Activation-induced cytidine deaminase (AICDA) and uracil DNA glycosylase (UNG) deficiencies specifically affect the CSR in B cells, presenting as a PAD known as hyper IgM syndrome with an increased incidence of hematologic cancers." (PMID 34484227, 2021). "The hyper-IgM syndrome is either an inherited X-linked PID due to mutations in the gene encoding CD40 ligand or autosomal recessive PID due to mutations in CD40, AID or UNG genes." (PMID 27642394, 2016). "A genetic defect in CD40, an autosomal recessive form, or its downstream signaling molecules such as activation-induced cytidine deaminase and uracil-DNA glycosylase, resulting in defects in CD40-mediated signal transduction in B cells, may also cause hyper IgM syndrome." (PMID 31426619, 2019).
Immunodeficiency (5 papers, 2017 to 2025). Failure of the immune system to protect the body adequately from infection, due to the absence or insufficiency of some component process or substance. "Of note, subfertility appears to be a species-specific defect as no fertility problems have been reported in Unga deficient mice, and the only human phenotype related to mutations in UNG is immunodeficiency with hyper-IgM type 5 (HIGM5) (OMIM: 608106)." (PMID 40981268, 2025). "Mutations in UNG are very rare and cause the immunodeficiency hyper-IgM type 5 (OMIM #608106)." (PMID 31507588, 2019). "UNG deficiency results in an immunodeficiency, but patients with CMMRD do not have an overt immunodeficiency." (PMID 31507588, 2019).
lymphoma (5 papers, 2019 to 2021). A malignant (clonal) proliferation of B- lymphocytes or T- lymphocytes which involves the lymph nodes, bone marrow and/or extranodal sites. "The low number of known patients carrying inactivating mutations in the UNG gene so far precludes an evaluation of the possible development of lymphomas caused by UNG mutations in humans." (PMID 33921666, 2021). "Here we have explored the contribution of AID and UNG to lymphoma generation by combining gain- and loss-of-function genetic mouse models." (PMID 33362210, 2020). "In contrast, mice lacking UNG activity are more susceptible to suffer lymphoma when AID is expressed at higher levels." (PMID 33362210, 2020). "There is no relation between them in the dataset but the result predicts that gemcitabine may help to prevent the development of lymphoma by restraining the expression of UNG." (PMID 31194807, 2019). "In a c-Myc-driven lymphoma mouse model the deficiency of UNG had no impact on lymphomagenesis." (PMID 32547565, 2020). "In contrast, in the absence of UNG, AID supra-expression increases SHM and promotes lymphoma." (PMID 33362210, 2020).
colon cancer (4 papers, 2012 to 2025). "This programmable strategy holds promise for selective gene editing in cells with elevated BER enzyme expression, such as uracil DNA glycosylase (UDG) in colon cancer cells." (PMID 40527291, 2025).
colorectal tumors (4 papers, 2016 to 2025). "Effects of UNG knockdown in BALB/c mice inoculated with CT-26 colorectal tumors." (PMID 40663394, 2025).
melanoma (4 papers, 2017 to 2025). A malignant, usually aggressive tumor composed of atypical, neoplastic melanocytes. "The varicella-zoster virus (VZV) UNG (ORF59) is dispensable for replication in human melanoma cells and monkey kidney fibroblast cells and a UNG inhibitor does not impact VZV replication." (PMID 37398059, 2023). "A study analyzing 95 melanoma patients treated with ICIs found that genes affected by VARs associated with hypophysitis include SMAD3, PRDM1, and IL1RN, while genes affected by CNVs related to the occurrence of hypophysitis are TERT, SMAD3, JAK2, PRDM1, FAN1, CD274, and UNG." (PMID 41465179, 2025). "These correlation results suggest a strong contribution of REV1, UNG, and possibly APOBEC3A to overall mutagenesis in sarcoma, melanoma, and renal cell carcinoma, respectively." (PMID 29642934, 2018).
autoimmune disease (3 papers, 2020 to 2023). A disorder resulting from loss of function or tissue destruction of an organ or multiple organs, arising from humoral or cellular immune responses of the individual to their own tissue constituents. "Except for Uracil-DNA glycosylase and GTP-binding protein LepA, other proteins were found to exhibit a link with either autoimmune disorders, infections, or both." (PMID 37513704, 2023). "Nevertheless, a large body of evidence, including work from our own laboratory, has demonstrated the critical function of UNG in CSR, including formation of class switched autoantibodies mediating autoimmune disease." (PMID 32264925, 2020). "Uracil-DNA glycosylase and GTP-binding protein LepA mimics were removed from the analysis, as they did not depict any role in autoimmune disorders." (PMID 37513704, 2023).
lymphoid neoplasm (3 papers, 2017 to 2025). A neoplasm composed of a lymphocytic cell population which is usually malignant (clonal) by molecular genetic and/or immunophenotypic analysis. "However, two cases of lymphoid tumours (more than 80% clonal based on TCR rearrangements) were previously found in a cohort of aged Smug1tm1a(EUCOMM)Hmgu−/−Ungtm1Tld−/− mice (hereafter referred to as UNG/SMUG1-DKO) at about 2 years of age12." (PMID 28775312, 2017).
prostate adenocarcinoma (3 papers, 2018 to 2025). "Elevated levels of UNG expression, but not of other candidate genes, were found in the prostate adenocarcinoma (PRAD; 10.15) and small cell lung cancer (SCLC; 10.10) cell lines." (PMID 29642934, 2018).
Alzheimer disease (2 papers, 2012 to 2024). A progressive, neurodegenerative disease characterized by loss of function and death of nerve cells in several areas of the brain leading to loss of cognitive function such as memory and language.
cervical carcinoma (2 papers, 2022 to 2023). A carcinoma arising from either the exocervical squamous epithelium or the endocervical glandular epithelium. "Higher expression of APOBEC3A and UNG in cervical cancer was associated with better outcomes (P = 0.039 and P = 0.019, respectively), according to TCGA." (PMID 38021159, 2023). "UNG rs246079 G/A might contribute to a decreased risk of esophageal cancer and an increased risk of cervical carcinoma." (PMID 35656315, 2022). "APOBEC3A and UNG expression levels were significantly higher in cervical cancer than in adjacent normal tissues, according to TCGA and GTEx (P < 0.001)." (PMID 38021159, 2023). "The APOBEC3A to UNG expression level ratio was significantly higher in cervical cancer than in intraepithelial lesion tissues (P = 0.002)." (PMID 38021159, 2023). "However, the ratio of APOBEC3A to UNG is also increased in tumor tissues, suggesting that the DNA damage-repair balance is disturbed in cervical cancer." (PMID 38021159, 2023).
coronary artery disease (2 papers, 2012 to 2017). "In conclusion, we discovered and confirmed a gain of the 10q24.31 (ERLIN1) and 12q24.11 (UNG, ACACB) genomic regions in patients with coronary artery disease and metabolic comorbidity." (PMID 28120895, 2017).
glioma (2 papers, 2022 to 2025). A benign or malignant brain and spinal cord tumor that arises from glial cells (astrocytes, oligodendrocytes, ependymal cells). "In our selection of seven HRD-related genes, the high expression of PLK3, PRMT6, UNG, and FANCB is associated with poorer prognosis in glioma patients, whereas the high expression of POLR2F, INO80D, and PTEN is linked to better prognosis." (PMID 41417782, 2025). "Glioma patients with high UNG high expression in the two immunotherapy cohorts showed better prognosis and clinical response." (PMID 36152044, 2022). "Our analysis also suggested that UNG regulated the tumor immune microenvironment and is a potential marker for evaluating the efficacy of immunotherapy in glioma patients." (PMID 36152044, 2022). "For instance, genes like UNG and PLK3 play a significant role in most glioma cell lines, whereas PTEN and INO80D exhibit a weaker influence in the majority of cell lines." (PMID 41417782, 2025).
lung adenocarcinoma (2 papers, 2020 to 2024). A carcinoma that arises from the lung and is characterized by the presence of malignant glandular epithelial cells. "Transcriptional upregulation of A3B and downregulation of UNG were subsequently validated in multiple oncogenic EGFR-driven cellular models of lung adenocarcinoma at both the RNA and protein levels." (PMID 38049664, 2024). "An increase in A3B and a decrease in UNG protein levels were detected in EGFR TKI-treated tumor tissues from three distinct oncogenic EGFR-driven CDX models of human lung adenocarcinoma." (PMID 38049664, 2024).
Non-small cell carcinoma (2 papers, 2020 to 2021). "The up-regulation of UNG is associated with pemetrexed resistance in non-small cell lung carcinoma, while UNG knockdown sensitizes these cells to pemetrexed." (PMID 34771075, 2021).
ovarian carcinoma (2 papers, 2014 to 2019). A malignant neoplasm originating from the surface ovarian epithelium. "We previously found that SNP rs34259 in the uracil‐DNA glycosylase gene (UNG) might decrease ovarian cancer risk in BRCA2 mutation carriers." (PMID 30747491, 2019). "The SNP rs34259 in the 3′UTR of the UNG gene may decrease ovarian cancer risk in BRCA2 mutation carriers." (PMID 30747491, 2019). "Given that the SNP protective effect is for ovarian cancer, we also determined UNG mRNA expression in tissues of 17 prophylactic oophorectomies from BRCA1 and BRCA2 mutation carriers." (PMID 30747491, 2019).
primary immunodeficiencies (2 papers, 2010 to 2018). "In particular, mutations in CD40LG, CD40, AICDA, or UNG cause hyper-IgM (HIGM) syndrome, a heterogeneous group of primary immunodeficiencies." (PMID 30131802, 2018). "ArfGEF plays an important role in vesicular transport for endocytosis, and UNG, uracil-DNA glycosylase, located in the pathway of primary immunodeficiency, and both genes showed higher up-regulation in PG/control confirmed by qPCR." (PMID 21203416, 2010).
prostate carcinoma (2 papers, 2017 to 2020). A carcinoma that arises from epithelial cells of the prostate gland. "The loss of UNG has been shown to be associated with the induction of apoptosis in human prostate cancer cells and display of increased sensitivity to genotoxic stress." (PMID 28846663, 2017). "Lupeol, a major bioactive compound of AVL extracts, inhibited the activity of UNG, which sensitized prostate cancer cells to cytotoxic stress induced by ethanolic extracts of AVL leaves." (PMID 28846663, 2017). "In addition, lupeol downregulated β-catenin signal during G2/M phase, and sensitized prostate cancer cells to cytotoxic stress of AVL extracts by the suppression of UNG activity." (PMID 28846663, 2017). "AVL F8 and lupeol could be a good candidate for prostate cancer synergistic therapy while using DNA-damaging drugs due to the alteration of UNG expression." (PMID 28846663, 2017).